ARG1 (arginase 1)
Diseases named in the same sentence as ARG1 in open-access papers (continued):
Sharing a sentence is not in itself a finding about the gene and the disease.
tumor (continued). "The lactate, produced also by tumor cells, activates HIF-1α, enhancing the expression of pro-tumorigenic genes [including VEGFA and Arginase 1 (ARG1)]." (PMID 40868256, 2025). "In the context of CRC, the NO pathway metabolites are found to be altered, with enzymes such as ARG1, PRMT1, and PRMT5 being overexpressed in both tumor and tumor-adjacent tissues." (PMID 41268067, 2025). "This activation increases the upregulation of the immune regulatory molecules PD‐L1 and arginase 1 (ARG1), thereby facilitating the survival of tumor cells." (PMID 40035165, 2025). "In parallel, the levels of their secreted immunosuppressive factors, including Arg-1, IDO and iNOS, were notably higher in tumor tissues." (PMID 41029721, 2025). "Acetate has been shown to promote progression by activating FFAR2 and triggering the Gαq/Ca2+/PPAR-γ/Arg1 signaling pathway in MDSC, drives an immunosuppressive phenotype that promotes tumor growth in lung adenocarcinoma models." (PMID 41339918, 2025). "Factors released from neutrophils, such as arginase-1, MMP-9 (matrix metalloproteinase-9), or VEGFs, can promote angiogenesis and tumor development." (PMID 40358184, 2025). "This inhibition leads to increased expression of ARG1 in MDSCs, thereby enhancing their immunosuppressive activity and facilitating immune evasion in CRC tumor microenviroment." (PMID 41020041, 2025). "After tumor - derived exosomal HSP70 binds to TLR2 on the surface of MDSCs, it activates STAT3 phosphorylation, induces the expression of arginase 1 (Arg1) and inducible nitric oxide synthase (iNOS), and enhances the immunosuppressive activity of MDSCs." (PMID 40297581, 2025). "High expression of Arg-1, COX-2, and iNOS after routinely fractionated radiotherapy with TAMs has also been found in a mouse model of prostate cancer to promote early tumor growth." (PMID 40356601, 2025). "This M2-like increase is consistent with findings from other studies, where tumor-infiltrating macrophages (both BMDMs and RAW264.7) exhibited an increase in Arg1 expression." (PMID 40634306, 2025). "Tumor-derived lactate drives transcriptional reprogramming (CCL2, ARG1, IL10, S100A9) in TAMs via the ENSA-K63la/STAT3-pY705 axis, promoting an immunosuppressive environment and immunotherapy resistance." (PMID 39883522, 2025). "HIF-1α is stabilized under hypoxic conditions and induces the upregulation of VEGF, ARG1, and MMP9, thereby reinforcing the immunosuppressive functions of TAMs and facilitating tumor invasion." (PMID 41002423, 2025). "For example, lactate, which is produced in large quantities by M1 macrophages, promotes tumor angiogenesis via hypoxia inducible factor 1α (HIF-1α) and upregulates VEGF and Arg1, thereby promoting M2 polarization." (PMID 40453088, 2025). "M2 macrophages express factors like arginase-1 and VEGFA, promoting angiogenesis, immunosuppression, and metastasis, while reducing the proportion of anti-tumor M1 macrophages." (PMID 40672391, 2025). "Transcriptomic and single-cell analyses have shown that ARG1 and ARG2 are expressed not only in GBM cells but also in tumor-infiltrating MDMs." (PMID 40800581, 2025). "The frequency of tumor-supporting CD206+MHCII+/− macrophages was increased, and TAMs showed higher arginase 1 (ARG1) expression, in accordance with an immunosuppressive phenotype." (PMID 40588561, 2025). "For instance, TAM-derived arginase 1 (Arg-1) depletes L-arginine, leading to downregulation of the T cell receptor (TCR) ζ chain and resulting in impaired function of tumor-infiltrating lymphocytes." (PMID 41584608, 2025). "Collectively, the CRC TME establishes “arginine starvation” through tumor-intrinsic uptake and MDSC/TAM-mediated ARG1 catabolism, creating an immunosuppressive niche that simultaneously impairs effector immunity and enriches regulatory populations." (PMID 41488637, 2025). "The expression of arginase-1 in neutrophils and the level of Apo-A1 within UTUC tumors were negatively correlated with tumor-infiltrating CD4+ T cells." (PMID 40358184, 2025).
tumor (continued). "Two isoforms of arginase, ARG1 and ARG2, are aberrantly expressed in various types of cancer and have been shown to play a crucial role in regulating tumor growth and metastasis." (PMID 41246357, 2025). "Biomarkers such as arginase-1 (ARG1) and argininosuccinate synthase 1 (ASS1) are differentially expressed and contribute to immunosuppressive tumor microenvironments, offering insight into immune evasion mechanisms." (PMID 41244835, 2025). "These M2-type TAMs secrete factors including transforming growth factor-β (TGF-β), interleukin-10 (IL-10), arginase-1 (ARG1), and vascular endothelial growth factor (VEGF), which further suppress anti-tumor immunity and promote angiogenesis." (PMID 41488637, 2025). "Upon being recruited to inflammatory tumor tissues in response to chemokines like CCL2, CCL5, CXCL8, and CXCL12, MDSCs rapidly produce immunosuppressive mediators, including ARG1, NO, TGF-β, and IL-10, which further impair anti-tumor immunity." (PMID 40563367, 2025). "Arg1 expression was dramatically decreased in MDI-2268, lucanthone, and combination treated tumors, within the tumor core and at the periphery." (PMID 40684232, 2025). "An eleven-marker panel (CD3, CD4, CD8, FOXP3, CD68, arginase-1, CD33, HLA-DR, pan-keratin (PanCK), PD-1, and PD-L1) was used to study the tumor and immune cell compositions." (PMID 38898200, 2024). "The direction of these changes was determined by analyzing the mRNA synthesis of specific factors (cytokines, Arg1, NOS2, Ido1) in TAS cells of tumor-bearing and other groups of the experimental mice." (PMID 38455363, 2024). "In this study, arginase-1 release was induced by non-small cell lung cancer (NSLC) cell culture supernatant, specifically tumor cell-produced IL-8 and TNF." (PMID 38786066, 2024). "Arg1 inhibits the cytotoxicity of T cells by depleting L-arginine, shifting T cell metabolism towards OXPHOS, ultimately contributing to tumor progression." (PMID 38713256, 2024). "The M2 macrophages secrete anti-inflammatory molecules, including resistin-like-α, IL-10, Arginase-1, and mannose receptor C type 1 (MRC1), which help in resolution of inflammation and remodeling of injured lung tissue and tumor progression." (PMID 39120378, 2024). "By immune phenotyping, we observed an upregulation in the expression of T cell-suppressive molecules, PD-L1, Fas Ligand (FasL), and ARG1 across moDC, M-MDSC, and G-MDSC subsets from day 5 to day 11 post-tumor induction." (PMID 38577107, 2024). "Arginase-1, produced by myeloid cells, impairs antitumor response, and CCL5, mainly expressed by T lymphocytes, macrophages, platelets, tumor cells and MDSCs, resulted in a direct CCR5-dependent recruitment of Treg cells in TME." (PMID 37142825, 2024). "The results showed that the presence of tumor-CM significantly increased binding of HES1, along with STAT6, to the Arg1 promoter, suggesting HES1 directly binds to the Arg1 promoter to lead its expression." (PMID 39702544, 2024). "By enhancing MCT-4 expression and the glycolytic rate, lactate promotes M2 polarization by inducing arginase-1 (Arg1), HIF-1α, IL-6, and transcriptional repressors such as ICER, which negatively influence anti-tumor responses." (PMID 38891772, 2024). "The remodeling of GAMs by lactate is manifested in the induction of VEGF and Arg1 expression via the HIF1-α signaling pathway, which promotes the polarization of GAMs toward M2 and assists GAMs in their pro-tumor function." (PMID 38632627, 2024). "The mRNA expression of Arg-1, IL-10, and CD163 were markly up-regulated in tumor samples compared to paracancer tissue samples." (PMID 38822362, 2024). "On the other hand, macrophages that express high levels of arginase-1 (ARG1), IL-10, CD163, CD204, or CD206 are considered to have pro-tumor effects." (PMID 39075441, 2024). "Neutrophil-like MDSCs accumulate in the tumor tissue of patients with PDAC, and CD13hi neutrophil-like MDSCs exert immunosuppressive effects through ARG1 expression." (PMID 38609997, 2024).
tumor (continued). "On the other hand, M2 macrophages, characterized by high expression of CD206, ARG1, and CD163, promote tumor progression by antagonizing anti-tumor T-cell immunity." (PMID 39719597, 2024). "In CRC, inhibition of PI3Kγ in MDSCs downregulates Arg1 and ROS leading to MDSC apoptosis and reduction in immunosuppression capacity, thereby allowing CD8+ T cells activation and tumour elimination." (PMID 38464388, 2024). "Upon the polarization of neutrophils via TGFβ, pro-tumor N2 phenotype showed a high expression of CCL17, ARG1, and CXCL14." (PMID 39061147, 2024). "In vivo therapy with anti-programmed cell death-1 Ab decreased ARG1+ TAM populations, which is consistent with another study on the TAM-mediated inhibition of tumor immunity via the expression of PD-1." (PMID 38540186, 2024). "In this regard, to characterize in detail the efficiency of mRNA expression, we chose two genes, Arg1 and TGF-β1, with distinctive differences in the efficiency of mRNA expression in intact mice, tumor-bearing mice, and treated experimental animals." (PMID 38455363, 2024). "For example, tumor-derived lactate induces macrophages to convert to M2 by stimulating STAT3 to activate endothelial growth factor (VEGF) and arginine (Arg-1), which further promote tumor development." (PMID 39683818, 2024). "Arg1 mRNA expression was present in two of the three Ddr2+ CAF clusters as well as in two immune cell clusters and one tumor cell cluster." (PMID 37996700, 2024). "We treated KLN205 tumor-bearing C57BL6 mice after BCG injection with a commercially available Arg-1 inhibitor (ABH) at a dose of 200 μg i.p. every 2 days for a total of 12 times, and tumor growth rate was monitored over 22 days." (PMID 38720340, 2024). "Meanwhile, macrophages can promote tumor invasion and metastasis through secretion of various cytokines (e.g., TGF-β, IL-10, arginase 1) and chemokines (e.g., CCL5, CCL17, CCL18, CCL22)." (PMID 38637499, 2024). "Tumors can also upregulate key catabolic enzymes like ARG1 or indoleamine 2,3-dioxygenase 1 (IDO1) in myeloid cells to deplete arginine and tryptophan within a tumor, which are crucial for regulating T-cell differentiation and proliferation." (PMID 38216787, 2024). "In contrast, N2 neutrophils are characterized by high expression of CXCR4, Arg-1, VEGF, and MMP-9, with their high levels of infiltration promoting tumor progression." (PMID 39648199, 2024). "Among them, M2a is induced by IL-4/IL-13 and secretes IL1-Ra, arginase-1 (Arg-1), TGF-β, CCL17, and CCL18, which inhibit M1-TAM polarization and promote tumor cell growth and metastasis." (PMID 39560523, 2024). "Upon flagellin treatment, flagellin reduced tumor growth along with an increase in the concentration of TNF-α, and higher mRNA levels of Tnfa, whereas the mRNA levels of Arg1 were reduced." (PMID 38331868, 2024). "In contrast, N2-type neutrophils express higher levels of immunosuppressive molecules such as Arg-1, IL-10, and TGF-β, thus inhibiting anti-tumor immunity." (PMID 39648199, 2024). "When interacting with tumor cells the mRNA expression of the M2‐like TAM marker, Arg1 was reduced, but the M1‐like TAM markers Nos2 and Ifn‐β were potentiated in the KO cells compared to the WT cells, which is consistent with the lactic acid treatment data." (PMID 38308188, 2024). "Such macrophages express high levels of Arg-1, TGF-β, and IL-10, which play an anti-inflammatory role and promote tumor cell proliferation, metastasis, angiogenesis and intravasation." (PMID 38970071, 2024). "Two genes related to a favourable immune response, ARG1 and HLA-DQB2, and the tumour markers CDKN2A and KRT7 were selected for validation with qPCR and further analysis." (PMID 39712018, 2024). "By up-regulating factors such as arginase 1 (ARG1) and CCL2, TGF-β promotes tumor growth and the potential for metastasis by facilitating the conversion of N1-type TANs to N2-type." (PMID 39456636, 2024).
tumor (continued). "Inhibition of tumor- or immunosuppressive cell-expressed GLS1, ARG1, iNOS, IDO1, TDO and/or IL4I1 therefore constitutes a promising approach to alleviate tumor-induced immune suppression, either as monotherapy or in combination with other treatment modalities." (PMID 39211039, 2024). "In lung cancer cell-challenged mice, increased CXCLs/CXCR2 signaling, Arg-1, and TGF-β levels were observed, accompanied by the significant infiltration of TANs in tumor tissues." (PMID 39061147, 2024). "We first compared the contents of M2 macrophage markers, Arg-1, IL-10, CD163, CD206, and CRNDE in tumor tissues and para-cancerous tissues." (PMID 38822362, 2024). "Arg1 17 and Ym1 18 are fundamental features of M2 macrophages, with the secretion of Arg1 19, Ym1 20, MMP2 21 and MMP9 22 by macrophages promoting the metastasis of tumor cells." (PMID 38356723, 2024). "We first analyzed M2 macrophage markers, such as Arg-1, IL-10, and CD163 in tumor and paracancer tissues." (PMID 38822362, 2024). "M2-TAM can secrete IL-10, arginase 1 (Arg-1), programmed death ligand 1 (PD-L1), TGF-β and VEGF, which are conducive to tumor growth." (PMID 38244580, 2024). "In the subcutaneous syngeneic tumor model, the signals secreted from tumor cells, e.g., in TCM from LLC cells and CT26 cells, induce ARG1/Arg1 expression in the host myeloid cells." (PMID 38422022, 2024). "In a similar manner to the in vivo tumor setting, TCM-treated M-MDSCs, which were the dominant cell type in these cultures, showed increased expression of PD-L1, ARG1, and SIRPα." (PMID 38577107, 2024). "A variety of tumor microenvironment (TME)-derived factors induce the upregulation of cationic amino acid transporter protein (CAT-2B) and ARG1 expression in MDSCs." (PMID 38609997, 2024). "Quantitative PCR on mRNA isolated from omental ID8TB−/− tumor nodules, different than those used for Nanostring analysis, confirmed that Arg1 mRNA was indeed decreased in ID8TB−/− and BPPNM tumor nodules from Ddr2−/− hosts." (PMID 37996700, 2024). "In CIN3 versus normal biopsies, the tumour markers CDKN2A and KRT7 had the highest fold-change, while genes related to a favourable immune response, ARG1 and NCAM1, had the lowest." (PMID 39712018, 2024). "The effects of NU7441 on the mRNA expression of DNA‐PK and functional markers of MDSCs (iNOS, Arg1, and IDO) in splenic MDSCs of tumor‐bearing mice were detected using qPCR." (PMID 36373232, 2023). "The mechanism of the drug action is aimed at blocking ARG1 in MDSCs, resulting in T lymphocyte active proliferation and increased CD8+ T cell tumor infiltration." (PMID 37185755, 2023). "Immunoregulatory cells that express the ARG1 protein in the TME, such as M2-like TAMs, tolerogenic DCs, and Treg cells, prevent T cells from accessing arginine, which inhibits anti-tumor immunity." (PMID 36677919, 2023). "Next, to determine if expression of ARG1 and AGMAT declines early in tumor development, we performed IHC on livers of 12- and 16-week-old L-dKO mice." (PMID 37804830, 2023). "The IF staining showed that the proportions of Arg-1+ cells and CD206+ cells were also enlarged in tumor tissues from CKO mice." (PMID 37733446, 2023). "In the early stages of tumor development, TAMs usually exhibit an M1 phenotype with high expression of iNOS and interleukin (IL)-12, and low expression of CD206, Arg-1 and IL-10." (PMID 37127625, 2023). "Tumor-promoting TAM2 are generally defined by the expression of scavenger receptors (e.g., CD204, CD206, CD163 or CD169) or ARG1." (PMID 36845555, 2023). "For example, glutaminase inhibitor CB-893, glutamine metabolism inhibitor JHU083, and arginase 1 inhibitor INCB001158 can not only inhibit tumor progression but also increase the immune system in TME cell infiltration." (PMID 36992704, 2023).
tumor (continued). "In murine tumor models, HDACi treatment significantly downregulates the expression of COX-2, ARG1, and iNOS in MDSCs." (PMID 38008741, 2023). "During anaerobic glycolysis, tumor cells secrete lactate, thereby favoring macrophage differentiation to the M2 phenotype, which in turn promotes tumor growth by liberating VEGF-A and arginase-1." (PMID 36670988, 2023). "The gene expression profile in CMS3 TME of KRASmut shows upregulation of CD40, CTLA4, ARG1, STAT3, IDO, and CD274, making it a key regulator of immune suppression in TME regions surrounding the KRASmut tumor." (PMID 36831441, 2023). "As compared to the control group, the expression of MR, ARG-1 and CCL17 were also upregulated, indicating that DCA can promote the polarization of M2 macrophages and in turn lead to tumor cell proliferation and intestinal tumorigenesis." (PMID 37943609, 2023). "A new peptide vaccine based on Arginase-1 combined with anti-PD1 has been shown to enhance T-cell infiltration in tumors and reduce the suppression of tumor-educated myeloid cells and change the M1/M2 ratio." (PMID 37376417, 2023). "Representative M2 markers include ARG1, CD163 and CD206, and the infiltration of M1 within the tumor is closely related to the poor prognosis of the tumor." (PMID 37762054, 2023). "By inducing the production of vascular endothelial growth factor (VEGF) and arginase-1 (Arg1) via the HIF1-signaling pathway, lactate can promote the polarization of TAMs to the M2 subtype and assist TAMs to promote tumor growth." (PMID 37795038, 2023). "At tumor sites, MDSCs release IL-10 and free radicals such as peroxynitrite, and they also express indolamine 2,3 dioxygenase (IDO1) and arginase-1 (ARG1)." (PMID 37189689, 2023). "Researchers have found that lactate produced by tumor cells induces overexpression of vascular endothelial growth factor as well as M2-like genes such as Arg1 in TAM, and that Arg1 expression in M2 macrophages is positively correlated with histone Kla levels." (PMID 37965331, 2023). "The authors suggest that targeting of PTEN by the miRNAs was responsible for the increase in the M2 markers, arginase-1 (ARG1) and transforming growth factor beta (TGF-β), promoting tumour growth." (PMID 37670020, 2023). "Myeloid cells with metabolizing arginase-1 and CD4+T cells related to tumors were found in the parenchymal region of the tumor." (PMID 36459212, 2023). "The regulation of ARG1 expression in MDSCs by IL-4, HIF-1α, and STAT3 is well established; however, the factors which regulate ARG2 in tumour cells have received less attention to date." (PMID 35962843, 2023). "Further, the contribution of different cell types to Arg-1 levels in plasma exosomes could change with the onset of tumorigenesis, with a higher relative amount of tumor cells releasing Arg-1 exosomes while keeping total exosomal Arg-1 levels at the same level as in non-tumor individuals." (PMID 38001706, 2023). "Second, TAMs promote tumor growth by inhibiting adaptive and innate antitumor immunity by secreting immunosuppressive molecules, including TGFβ, IL10, arginase-1 (Arg-1) and NO." (PMID 37206921, 2023). "In PC-3 tumor nodules harvested on day 8 after injection, the enhanced leukocyte infiltrate in ITGB4 KD tumors was again visible, characterized by arginase-1- and myeloperoxidase (MPO)-positive cells." (PMID 36932441, 2023). "The stromal cells along with tumor cells release a host of immunosuppressive cytokines including TGF-β, IL-10, ARG-1, inducible nitric oxide synthase, COX2, PGE2, FAP, and PD-L1 to help the tumor evade CAR T cells." (PMID 37509394, 2023). "Recently, we discovered that IL-6 produced in the tumor microenvironment augmented arginase-1 (ARG1) activity, and blockade of ARG1 significantly reduced tumorigenesis in a tumor-bearing model." (PMID 36639644, 2023).